IDH1 (isocitrate dehydrogenase (NADP(+)) 1)
Diseases named in the same sentence as IDH1 in open-access papers (continued):
Sharing a sentence is not in itself a finding about the gene and the disease.
glioblastoma (continued). "The current study included cases starting from 2001, while MGMT promotor methylation and IDH1 mutation statuses were first introduced to classify glioblastoma prognosis in 2005 and 2009, respectively." (PMID 34459971, 2021). "Although O-6-methylguanine–DNA methyltransferase (MGMT) promote methylation and the status of the IDH1 mutation seem to show correlation with longer survival, recurrence of glioblastoma patients is almost common." (PMID 33525678, 2021). "It has also been suggested to treat patients with IDH1mt glioblastoma with inhibitors of the mutated protein of IDH1." (PMID 33810170, 2021). "Among clinicopathological features of patients, except for KPS and IDH1, other characteristics are also crucial factors associated with the development of glioblastoma." (PMID 34606414, 2021). "Neuropathological examination confirmed an unmethylated but isocitrate dehydrogenase 1 (IDH1) R132H-mutated glioblastoma with a high proliferation rate (MIB‐1: 15–20% immunopositive tumor cells)." (PMID 33625551, 2021). "IDH1 mutation is a definitive diagnostic molecular marker in secondary glioblastoma compared to primary glioblastoma." (PMID 34066132, 2021). "In 2008, for the first time, Parsons and colleagues have demonstrated IDH1 mutations in the human genome related to the glioblastoma multiforme." (PMID 32373065, 2020). "IDH1/2 mutations are found in about 5% of glioblastomas and are associated with longer patient survival." (PMID 33396284, 2020). "On the other hand, only 7.4% of the G-CIMP glioblastomas showed loss of MTAP, which is associated with secondary glioblastoma, tumor-harboring mutation of the IDH1 gene, and lesions that progressed from LGG." (PMID 32093414, 2020). "The glycolysis score represented by expression of ten glycolytic genes predicted unfavorable clinical outcome for patients with glioblastoma and was closely related to mesenchymal subtype and mutation of IDH1 in glioblastoma." (PMID 32467671, 2020). "It is worth noting that the overexpression of IDH1 as well as mutations of this protein are most frequently found in a primary and secondary glioblastoma." (PMID 32110969, 2020). "Some cancers, such as glioblastoma, chondrosarcoma, leukemia and colorectal cancer, have mutations in isocitrate dehydrogenase 1/2 (IDH1/2)." (PMID 32111066, 2020). "In fact, IDH1/2 mutations are indicators of good prognosis in astrocytomas and glioblastomas since these mutations can lead to improved responses to irradiation and chemotherapy." (PMID 33333852, 2020). "Analysis of TCGA data demonstrates that IDH1 is upregulated in several malignancies, including anaplastic large cell lymphoma, glioblastoma, and pancreatic ductal adenocarcinomas, and it is associated with poor prognosis among leukemia patients." (PMID 32408513, 2020). "While H3.3K27M, IDH1 mutations are detected in a small fraction of glioblastoma patients, the mechanism by which oncogenic mutations remodel the epigenome are still poorly understood." (PMID 32051553, 2020). "Female patients with IDH1 mutation, known as a good prognostic marker in glioblastoma, mostly clustered in a single group with longest survival, whereas male patients with IDH1 mutation were distributed across all male clusters." (PMID 33330090, 2020). "We apply the method in an untargeted, discovery-driven workflow to investigate the metabolic effects of isocitrate dehydrogenase 1 (IDH1) mutations in glioblastoma cells." (PMID 32433536, 2020). "Using this approach, they identify metabolites altered in glioblastoma cells with mutations in isocitrate dehydrogenase 1 (IDH1)." (PMID 32433536, 2020). "Heterozygous somatic mutations in IDH1/2 have been identified in numerous cancers, strikingly at high frequency in glioblastoma multiforme and acute myeloid leukemia (AML)." (PMID 31105869, 2019).
glioblastoma (continued). "The IDH1 mutation is associated with better survival in glioblastoma patients (3.8 years) versus wild-type IDH1 (1.1 years)." (PMID 30708988, 2019). "Mutations at Arg132 of IDH1 are present in five of six secondary glioblastoma (GBM) subtypes, and IDH mutations have been found in many other solid tumors." (PMID 31803734, 2019). "Compared to these molecular markers in NCCN guideline (G_CIMP and IDH1) and previous reported prognostic signatures, the 111 methyl-probes showed more efficiency in glioblastomas risk clarification." (PMID 31708732, 2019). "For example, in highly vascularized glioblastoma, it has been shown that IDH1 mutations are associated with lower expression of VEGF and improved overall survival." (PMID 31632393, 2019). "The detection of IDH1/2 mutation is predominantly on diffuse astrocytomas, anaplastic astrocytomas, and secondary glioblastomas, but rarely identified on primary glioblastomas." (PMID 31450822, 2019). "Generally, IDH1 mutation is found less in primary glioblastoma patients (5%), but more in high grade glioblastomas (70–80%)." (PMID 30669406, 2019). "The incidence of IDH1/2 mutations in primary glioblastoma is approximately 5%, but in recurrent glioblastoma, the incidence is approximately 84.6%." (PMID 30777100, 2019). "In this large-scale analysis of IDH1-wt glioblastomas, tumor location was associated with a distinct growth and recurrence pattern and patient outcome, significantly contributing to the heterogeneous nature of this disease." (PMID 30669568, 2019). "In previous studies and by using transduced malignant glioma cell lines U-251MG (glioblastoma) U-343MG (anaplastic astrocytoma) and LN-229 (glioblastoma) we showed that gene expression of mutated IDH1 (IDH1R132H) resulted in elevated radiosensitivity." (PMID 31242696, 2019). "The incidence ofthe IDH1 mutation in low-grade diffuse astrocytomas andsecondary glioblastomas is 88% and 82%, respectively, with the TP53mutation being detected in 63% of diffuse astrocytomas." (PMID 31413876, 2019). "The project’s related publications include information on IDH1 mutations to be rare for childhood glioblastoma." (PMID 30675185, 2019). "Paradoxically, glioblastoma patients whose tumors harbor mutated IDH1/2 respond better to temozolomide." (PMID 31105869, 2019). "As expected, both oligodendrogliomas and astrocytomas were distinguished from glioblastomas by the p.IDH1-R132H mutation." (PMID 31747973, 2019). "A new variant, epithelioid glioblastoma, falls under IDH1-wild type and is characterized by the presence of large epithelioid cells, vesicular chromatin, rhabdoid cells and prominent nuclei." (PMID 30327965, 2018). "This can explain why IDH1/2 mutated glioblastomas and SDHB mutated paraganglioma and pheochoromocytoma are more sensitive to TMZ regiments and are associated with better prognoses." (PMID 29342092, 2018). "(iii) A “proneural” group of glioblastomas characterized by mutations of IDH1 displaying high levels of Olig2 and PDGF-Rα." (PMID 30279357, 2018). "Recurrent mutations in IDH1 were identified in 2008 during an integrated genomic analysis of a set of human glioblastoma tumor samples, and subsequently IDH2 was identified in 2009 in a set of glioma tumor samples." (PMID 29882807, 2018). "In glioblastoma patients, it has been reported that IDH1 mutations result in about a 2-fold decrease in NADPH production by wild-type enzyme." (PMID 29320744, 2018). "Although similar attempts have been made to identify IDH1/2 mutation and 1p/19q codeletion via radiomics, most of them included glioblastomas within the analyzed cohort, and only several of them focused on grade II/III gliomas." (PMID 30082856, 2018).
glioblastoma (continued). "The respective explanations for these outcomes are that ZEB1 loss results in the increase of stemness of the glioblastoma whereas the IDH1R132MUT results in inactivation of IDH1 from the use of isocitrate as a metabolic substrate." (PMID 30705664, 2018). "Another important finding of the initial studies on genetic abnormalities of glioblastomas was the observation that the R132 mutation of isocitrate dehydrogenase 1 (IDH1) was observed in 12% of samples." (PMID 30279357, 2018). "Mutations in IDH1 associated with glioblastomas map to the highly conserved residue R132, resulting in an Arg (R) to His (H) substitution." (PMID 29642503, 2018). "Cancer whole-genome sequencing efforts from Parson and colleagues revealed the presence of heterozygous, somatic, monoallelic, missense, point mutations in IDH1 in a glioblastoma (GBM) patient in 2008." (PMID 29439493, 2018). "Even at this early stage of the molecular understanding of glioblastoma, statistically significant correlations are seen between our imaging subtypes and the four molecular subtypes, as well as EGFRvIII and IDH1 mutation status, and MGMT methylation status." (PMID 29572492, 2018). "Single somatic mutations of the isocitrate dehydrogenase 1 (IDH1) gene, predominantly R132H, occurred in ~80% of LGGs as well as in secondary glioblastomas." (PMID 27852048, 2017). "We recently showed that the IDH1 R132H mutation reduces the proliferation and invasion of human glioblastoma cells, indicating a tumor suppressor function." (PMID 28445981, 2017). "In our study, IDH1 mutations have been identified in 8 cases among 65 studied glioblastomas (12.31%)." (PMID 28785587, 2017). "U87MG and murine glioblastoma cells bearing the IDH1 mutation showed decreased expression of Mcl-1, Bcl-xL, and Bcl-2." (PMID 29057925, 2017). "In this study, we utilized the concept of synthetic lethality to efficiently target glioblastomas bearing the IDH1 mutation." (PMID 29057925, 2017). "They inferred key genes associated with glioblastoma including IDH1, and showcased the potential of genome-wide genetic studies in opening novel avenues in brain cancer research." (PMID 28458684, 2017). "Due to higher prevalence of favorable mutations, such as the isocitrate dehydrogenase 1/2 (IDH1/2) gene mutations, the prognosis and survival for these patients are slightly better than for patients with de novo (primary) glioblastoma." (PMID 28730289, 2017). "In this study, we investigated which genes are differentially regulated in IDH1 wild type (IDH1WT) or IDH1 R132H mutation (IDH1R132H) glioblastoma cells." (PMID 28445981, 2017). "In an orthotopic glioblastoma xenograft model expressing mutated IDH1, Bcl-xL inhibition leads to long-term survival." (PMID 29057925, 2017). "The presence of IDH1 mutations has been indicated to be much more frequent in secondary glioblastomas compared to primary glioblastomas." (PMID 31548536, 2017). "Transduced U87MG and T98G glioblastoma cells, bearing the wild-type or mutated form of IDH1 were treated with increasing concentrations of the BH-3 mimetic ABT263, a known inhibitor of both Bcl-xL and Bcl-2." (PMID 29057925, 2017). "Based on these findings, we analyzed the metabolic phenotype of IDH1 wild-type and IDH1 R132H-mutated glioblastoma cells." (PMID 29057925, 2017). "In agreement, IDH1 R132H-mutated or 2-HG-treated glioblastoma cells showed less mitochondrial respiration and significant reduction in ATP production." (PMID 29057925, 2017). "Anaplastic astrocytoma samples with mutated IDH1 display lower levels of Mcl-1 than IDH1 wild-type tumors and specific knockdown of Mcl-1 broadly sensitizes glioblastoma cells to Bcl-xL inhibition-mediated apoptosis." (PMID 29057925, 2017). "Mutations of IDH1 (codon 132) or IDH2 (codon 172) allow discrimination between two classes of glioblastoma (GBM), IDH-wildtype and IDH-mutant, with differing genomic and epigenomic landscapes and prognoses." (PMID 28915660, 2017).
glioblastoma (continued). "A high proportion of low-grade gliomas and secondary glioblastomas have been shown to harbor mutations in isocitrate dehydrogenase 1 and 2 (IDH1/IDH2)." (PMID 28401060, 2017). "IDH1 mutational status has been shown to be a positive prognosticator for survival in patients with glioblastoma." (PMID 28401060, 2017). "As per The Cancer Genome Atlas (TCGA) Research Network, the proneural molecular subgroup of glioblastoma encompasses tumors which harbor IDH1 mutations and alterations in PDGFRA5." (PMID 29062039, 2017). "For instance, the Lai group demonstrated that IDH1 mutations render glioblastoma cells more sensitive to radiation." (PMID 29057925, 2017). "To date, all work concerning the use of temozolomide (TMZ) in combination with a PLK1 inhibitor has been in the context of primary grade IV glioblastoma, which rarely carries an IDH1 mutation." (PMID 28178660, 2017). "In this report, we demonstrate that inhibition of Bcl-xL causes synthetic lethality in IDH1-mutated glioblastoma cells in vitro and in vivo and that these effects are mediated by the oncometabolite, 2-HG, which reduces Mcl-1 protein levels." (PMID 29057925, 2017). "We have previously shown that the IDH1 R132H mutation reduces glioblastoma progression by inhibiting Wnt/β-catenin signaling." (PMID 28445981, 2017). "One of these inhibitors is AGI-5198, which in model systems of IDH1-mutated glioblastomas caused a significant reduction in the levels of 2-HG11." (PMID 29057925, 2017). "In six model systems, including patient-derived stem cell-like glioblastoma cultures, inhibition of Bcl-xL induces significantly more apoptosis in IDH1-mutated cells than in wild-type IDH1 cells." (PMID 29057925, 2017). "Our in vitro data showed an enhanced anti-neoplastic activity of ABT263 in IDH1-mutated glioblastoma cells." (PMID 29057925, 2017). "Glioblastoma (GBM) cells are often characterized by the presence of the IDH1 R132H mutation and high expression of anti-apoptotic proteins." (PMID 29057925, 2017). "Isocitrate dehydrogenase 1 (IDH1) gene mutations have been observed in a majority of diffuse astrocytomas, oligodendrogliomas, and secondary glioblastomas, and the mutant IDH1 R132H is detectable in most of these lesions." (PMID 31548536, 2017). "When mutated in glioblastoma, IDH1/2 yield another oncometabolite, 2-hydroxyglutarate (2-HG), from 2-oxoglutarate (2-OG) (also known as α-ketoglutarate)." (PMID 28424758, 2017). "Proneural glioblastoma is associated with elevated plasma membrane levels of platelet-derived growth factor receptor and often have isocitrate dehydrogenase 1/2 (IDH1/2) mutations." (PMID 28424758, 2017). "Our findings suggest that in solid tumors, such as glioblastomas, the inhibition of Bcl-xL elicits synthetic lethality in IDH1-mutated neoplasms." (PMID 29057925, 2017). "In an additional methylation analysis of the PD-L1 promoter region, a hypermethylation in IDH1/2 mutated patients was found, possibly explaining the downregulation of PD-L1 expression in proneural glioblastoma, which are partly G-CIMP." (PMID 28178682, 2017). "An interesting gene found to contain mutations in glioblastoma is IDH1, which encodes IDH1 and is involved in energy metabolism." (PMID 26858939, 2016). "Mutational status of BRAF, H3F3A, HIST1H3B and IDH1 were examined in all 107 young adult glioblastomas." (PMID 26452024, 2016). "The recent discovery of activating mutations in isocitrate dehydrogenase (IDH1) in glioblastoma demonstrates that an activating mutation in a metabolic enzyme are selected during carcinogenesis." (PMID 27565572, 2016). "We found expression of mutated IDH1 in few glioblastoma cases, which is in concordance with previous studies." (PMID 26839018, 2016). "IDH1 mutations were originally reported as frequent events in glioblastomas as well as acute myeloid leukemia." (PMID 26943575, 2016).
glioblastoma (continued). "Integrated genomic analysis identified recurrent mutations in the active site of IDH1 in 12% of glioblastoma multiforme patients." (PMID 26668680, 2016). "As expected, IDH1 mutated glioblastomas showed favorable prognosis in our cohort which was independent of age, tumor location, operation and adjuvant treatment among the young adult patients." (PMID 26452024, 2016). "Data summarized from many studies show that only approximately 5.6% of primary glioblastoma are IDH1 mutant, while more than 76% of secondary glioblastomas carry the IDH1 mutation." (PMID 26858939, 2016). "The IDH1 mutation predicts secondary glioblastoma better than these other mutations predict their respective glioblastoma subtype." (PMID 26858939, 2016). "In primary glioblastoma, IDH1 mutational status has been reported to be the only factor that showed significant association with patient survival times." (PMID 26858939, 2016). "Particularly, the discovery of recurrent mutations in the isocitrate dehydrogenase 1 (IDH1) gene has shed new light on the molecular landscape in glioblastoma." (PMID 26858939, 2016). "IDH1 mutation was present in 16.8% of young adult glioblastomas of which the mutation frequency was comparatively higher than the predominant group of adult/elderly glioblastoma as well as pediatric glioblastomas." (PMID 26452024, 2016). "IDH1 mutations are present in the vast majority of low-grade diffuse astrocytoma, as well as in secondary glioblastoma." (PMID 27253461, 2016). "Collectively, our study provided complementary evidence to previous studies that IDH1 mutated glioblastoma was a glioblastoma subgroup with favorable prognosis prevalent in adolescents and young adults." (PMID 26452024, 2016). "Mutations in IDH1 were first described in a whole-genome sequence analysis of glioblastoma patients." (PMID 27014635, 2016). "The majority of patients exhibited the R132C IDH1 mutation, in contrast to most secondary glioblastoma, which harbor the R132H mutation." (PMID 26858939, 2016). "Studies have shown that IDH1 mutation convey an improved prognosis with respect to both overall survival and progression-free survival for the rare glioblastoma patients who express this mutation." (PMID 26858939, 2016). "Extensive research has been performed to determine the prognostic value of IDH1 mutations, and a better prognosis has been generally reported in glioblastoma patients carrying an IDH1 mutation." (PMID 26858939, 2016). "This analysis also showed significant increases in gene sets specific to human glioblastomas, including the proneural sub-type, which is characterized by mutation of IDH1." (PMID 27693047, 2016). "Further comparison of patient age between the mutually exclusive molecular subgroups also revealed that BRAF mutated glioblastomas were younger than IDH1 mutated glioblastomas (mean age 22.3 years vs 27.9) (p = 0.0008, One-way ANOVA)." (PMID 26452024, 2016). "One of the most exciting and clinically relevant observations was the discovery that a high percentage of secondary glioblastomas and a very small percentage of primary glioblastoma harbor mutations in the isocitrate dehydrogenase 1 (IDH1) gene." (PMID 26858939, 2016). "IDH1 mutations are known as an important diagnostic marker, especially for low graded tumors and secondary glioblastoma." (PMID 26839018, 2016). "The frequency of IDH-1 mutations ranged from 4-7.6% in primary glioblastoma and 73-88% in secondary glioblastoma." (PMID 27120786, 2016). "Combining BRAF, H3F3A and IDH1 mutations allowed stratification of young adult glioblastomas into four prognostic subgroups." (PMID 26452024, 2016).